ALKBH5 (alkB homolog 5, RNA demethylase)
Diseases named in the same sentence as ALKBH5 in open-access papers (continued):
Sharing a sentence is not in itself a finding about the gene and the disease.
cancer (continued). "Experimental findings from cancer mouse models demonstrate that genetic and pharmacologic inhibition of distinct epigenetic factors, such as CECR2, ALKBH5, and EZH2, impairs tumor progression by reducing TAM infiltration and immunosuppressive polarization." (PMID 39133578, 2024). "Among m6A regulators, METTL3/14, FTO, ALKBH5, and members of the YTHDF family have been extensively studied for their contributions to RNA regulation and cancer progression." (PMID 39247830, 2024). "In AML, overexpressed ALKBH5 post‐transcriptionally reduces the stability of TACC3, AXL and ITPA transcripts to promote cancer stem‐cell self‐renewal." (PMID 38545841, 2024). "Hypoxia promotes the expression of HIF-1α and ALKBH5; ALKBH5 regulates the expression of ITGB1 in an m6A-YTHDF2-dependent manner, triggers the phosphorylation of FAK and Src, and promotes EOC cancer lymphangiogenesis and metastasis." (PMID 36632222, 2023). "Intriguingly, the present study has systematically illustrated the cancer‐related behaviour of RAB5A, a member of the Rab GTPases subfamily, and its upstream relation with the m6A‐modulator ALKBH5." (PMID 37203239, 2023). "The intricate interplay between molecules like ALKBH5, PHF20, DDIT4-AS1, and circCPSF6 underscores the complexity of cellular processes and their implications in diseases such as cancer." (PMID 38148841, 2023). "A previous study demonstrated that upregulated expression of ALKBH5 regulates AURKB mRNA expression in an m6A-dependent manner, thereby promoting cancer cell proliferation, migration, and invasion, leading to increased RCC volume and poor prognosis." (PMID 38117350, 2023). "Through a series of validations, we found that the ALKBH5/CHAC1/GSH axis has a role in regulating the level of ROS and apoptosis in cancer cells." (PMID 38007439, 2023). "Targeting dysregulated ALKBH5 and FTO is an appealing therapeutic approach for cancer in light of their essential functions in various malignancies." (PMID 37007161, 2023). "For example, a recent study showed that the collaboration of a set of WERs of m6A (‘writer: METTL14’, ‘eraser: ALKBH5’ and ‘reader: YTHDF3’) regulates cancer growth and progression." (PMID 36300630, 2023). "The representative m6A methyltransferases and demethylases, such as ALKBH5, METTL3, and METTL14, have been widely studied in cancer development." (PMID 37647025, 2023). "Depletion of ALKBH5 increased the levels of the UPR sensor proteins PERK, ATF4, ATF6, and IRE-α in normal and cancer cell lines." (PMID 37174684, 2023). "An increasing number of studies have confirmed that m6A writers (METTL3, METTL14, KIAA1429, WTAP), erasers (FTO and ALKBH5) and readers (YTHDC1, YTHDC2, YTHDF1, YTHDF2 and HNRNPC) have distinct functions within different types of cancer cells." (PMID 35042525, 2022). "The ALKBH5-mediated m6A modification led to DDIT4-AS1 overexpression in PDAC, and DDIT-AS1 increased cancer stemness and suppressed chemosensitivity to GEM by destabilizing DDIT4 and activating the mTOR pathway." (PMID 36056355, 2022). "Most m6A methyltransferases and demethylases have been intensively investigated in cancers, such as METTL3, METTL14, FTO, and ALKBH5." (PMID 35596159, 2022). "Together with the prognostic value of ALKBH5 in NSCLC, these observations suggested that ALKBH5 played a cancer-promoting role by regulating cell proliferation." (PMID 35318440, 2022). "further demonstrated that ALKBH5 remarkably enhanced the KCNK15-AS1 expression through decreasing the m6A level and stabilizing the KCNK15-AS1 mRNA, thereby suppressing cancer development." (PMID 35936737, 2022). "For instance, lncRNA FOXM1-AS functions as a scaffold to increase the ability of ALKBH5 to bind to its antisense mRNA FOXM1, providing both tumorigenic and proliferative advantages to cancer cells." (PMID 35063010, 2022). "In CRC, all readers and most writers and erasers show cancer-promoting effects, except for METTL3, METTL14 and ALKBH5." (PMID 35945641, 2022).
cancer (continued). "The enrichment analyses showed that the Alkbh5-altered genes were clustered in the PI3K/AKT pathway, mitogen-activated protein kinase signaling pathway, and pathways in cancer." (PMID 35784864, 2022). "ALKBH5 regulates FOXM1, G6PD, SOX2, and AKT2 expression in an m6A-dependent manner to promote cancer cell proliferation, invasion and drug resistance." (PMID 35945641, 2022). "However, whether ALKBH5 regulates angiogenesis in human cancers is still unclear." (PMID 36376862, 2022). "This highlighted the crucial role of ALKBH5 in maintaining cancer stem cell (CSC) renewal and cancer occurrence and development through the KDM4C-ALKBH5-AXL Signaling Axis." (PMID 36035182, 2022). "Another study suggested that m6A RNA modification catalyzed by enzymes including ALKBH5 and FTO had a fundamental role in the regulation of PI3K/Akt/mTOR signaling pathway in cancer." (PMID 35371987, 2022). "Hypoxia, c-Myc, the Wnt/β-catenin signaling pathway, the m6A “eraser” ALKBH5, and miR-3436 were reported to regulate YTHDF1 expression in cancer research." (PMID 36550542, 2022). "Thus, pharmacological inhibition of ALKBH5 may exert antitumor effects in these cancer types." (PMID 35063010, 2022). "We first elucidated the expression characteristics of these regulators in a pan-cancer context: (i) Expression changes of some clusters (YTHDF family, IGF2BP family, METTL14, FTO, and ALKBH5) were consistent in selected cancers." (PMID 33718187, 2021). "ALKBH5 also functions as an m6A demethylase, and increases the expression of its key target, FOXM1 (forkhead box M1), to promote the development of cancers by reducing m6A abundance on target mRNA transcripts (especially at the 3′ UTR)." (PMID 33692753, 2021). "ALKBH5 was upregulated in cisplatin-resistant EOC and promoted cancer cell cisplatin resistance both in vivo and in vitro." (PMID 34496932, 2021). "Subsequently, m6A RNA methylation erasers, FTO and ALKBH5, were identified to be dysregulated in HNSCC and other cancers." (PMID 34207099, 2021). "Studies have revealed that METTL14 and ALKBH5 control the expression of each other and inhibit the expression of YTHDF3, thereby blocking RNA demethylation to degrade cancer cells." (PMID 33628845, 2021). "Since our RT-qPCR results verified the expression of ALKBH5 and YTHDF1 in 12 pairs of cancer and normal tissues, we inferred Cluster 1 to represent the overall immunological characteristics of COAD, thus showing poor immune response." (PMID 34079761, 2021). "Curiously, our results on m6A eraser expression are in line with those reported for other cancers, in which FTO and ALKBH5 were also found to be overexpressed." (PMID 34683137, 2021). "METTL14 was down-regulated in all 11 cancer types while FTO and ALKBH5 were down-regulated in most cancer types except for KIRC." (PMID 33718187, 2021). "ALKBH5 was reported to be overexpressed in EOC tissues and promoted cancer progression by inhibiting EOC cell autophagy." (PMID 34496932, 2021). "ALKBH5 promoted renewal and growth of breast cancer cells by reversing m6A of NANOG mRNA, which in turn enhanced the stability of NANOG and stemness of cancer cells." (PMID 32209098, 2020). "The lncRNA GAS5-AS1 increases the expression of the tumor suppressor growth arrest specific 5 (GAS5) via the ALKBH5-m6A-YTHDF2 axis, regulating cancer growth and metastasis." (PMID 32709063, 2020). "m6A was reported to be involved in the EMT of cancer cells and modulated via the methyltransferase METTL3, demethylase ALKBH5, and its reader YTHDF1." (PMID 33364952, 2020). "We also found that the mRNA and protein levels of YAP were higher, while those of ALKBH5 were lower, in NSCLC cancer cells than in the control (normal) cells BEAS-2B." (PMID 32106857, 2020). "Declined mRNA levels of ALKBH5 and FTO were related to a shortened overall and cancer-specific survival following nephrectomy." (PMID 33015074, 2020).
cancer (continued). "Specifically, ALKBH5 suppresses the BCL-2 expression, which was demonstrated to inhibit autophagy in cancer." (PMID 32258108, 2020). "Low expression of ALKBH5 in pancreatic cancer cells reverses the m6A modification of lncRNA KCNK15‐AS1, resulting in a decrease in the ability of cancer cells to invade and metastasize." (PMID 33029866, 2020). "Our data demonstrate that targeting ALKBH5 increases radiosensitization of GBMSCs and represses their invasion capability and suggest that ALKBH5 is an attractive therapeutic target to overcome radioresistance and invasiveness of GBM cancer cells." (PMID 33375621, 2020). "Interestingly, the oncometabolite D-2-hydroxyglutarate (D2-HG), which could act as a nonspecific inhibitor of the iron- and αKG-dependent dioxygenases FTO and ALKBH5, accumulates in about 20% of AMLs, and may thus contribute to the outcome of these cancers by inhibiting RNA demethylation." (PMID 29061143, 2017). "Inhibition of the RNA demethylases ALKBH5 and FTO is a potential strategy to target cancer stem cells." (PMID 28533023, 2017). "ALKBH5 plays a dual role in various cancers, impacting positive and negative substrates by regulating kinds of biological processes." (PMID 39781264, 2025). "In addition, ALKBH5-mediated m6A demethylation of FOXO1 mRNA stabilizes its transcript, restoring redox homeostasis and promoting cancer stem cell traits and doxorubicin resistance in triple-negative breast cancer." (PMID 40986143, 2025). "The synergy between MALAT1 and ALKBH5 was consistently observed in stage four across four cancers but exhibited negative correlations in KIRP and SKCM, while showing positive correlations in STAD and THCA." (PMID 40728857, 2025). "Finally, considering VEGFA is secreted to promote cancer angiogenesis, we also test the VEGFA levels in the culture medium of sh-ALKBH5 U87 cells, and results also indicated knock-down ALKBH5 in U87 cells will lead to less VEGFA expression and secretion." (PMID 38221546, 2024). "ALKBH5-mediated FOXO1 m6A demethylation increases the expression of superoxide dismutase 2 and leads to a lower ROS level, thus promoting the maintenance of cancer stem cell characteristics and doxorubicin resistance in TNBC." (PMID 39054967, 2024). "ALKBH5, by reducing m6A, enhances ubiquitin‐specific protease 1 (USP1) expression that regulates chemoresistance by upregulating Aurora B. Thus, m6A modification regulates apoptosis in cancer therapy resistance." (PMID 39661414, 2024). "Furthermore, m6A RNA levels in the PB of MC38 cancer models were upregulated, whereas the expression of FTO and ALKBH5 decreased." (PMID 38439072, 2024). "We postulate that a similarly conserved epitranscriptomic mechanism involving m6A235 demethylating activity by ALKBH5 and/or FTO may contribute to the induction of ATF4 mRNA expression in cancer cells under stress conditions." (PMID 39199320, 2024). "Similarly, in our study, knocking down ALKBH5 increased the expression of ABCA1 and decreased autophagy substrate SQSTM1, which activated autophagy-related pathways for anti-cancer effects." (PMID 38481816, 2024). "In numerous cancers, there is a consistent observation of dysregulated expression of key enzymes involved in m6A modification, including "writers" (such as METTL3, METTL14, WTAP), "erasers" (like FTO, ALKBH5), and "readers" (including YTHDF1, YTHDF2, YTHDF3)." (PMID 38270643, 2024). "A large number of studies of m6A regulatory mechanisms have investigated classical m6A regulators, such as METTL3, METTL14, WTAP, METTL16, FTO, ALKBH5, YTH family proteins, and IGF2BPs; anti-cancer target drugs targeting METTL3 and FTO have been proven to be effective against cancer." (PMID 38970366, 2024). "Studies have shown that upregulation of ALKBH5 in cancer cells can enhance the translation efficiency of FOXM1 mRNA, leading to increased FOXM1 protein expression and promoting the proliferation and invasion of cancer cells." (PMID 38094306, 2023).
cancer (continued). "Serum deprivation dramatically decreased the cellular ALKBH5 K235 acetylation level in cancer cells within 24 h but did not alter the ALKBH5 level." (PMID 37369679, 2023). "In summary, we show that ALKBH5 is important in regulating ERLIN1-IP3R-dependent calcium flux between ER and mitochondria, and consequently, AMPK activation and mitochondrial biogenesis in both normal and cancer cells." (PMID 37174684, 2023). "Interestingly, consistent with the dual role of ALKBH5 played in tumors, FABP5 seems also function contradictory effect in different cancers." (PMID 37858219, 2023). "The m6A-dependent modification is reversible and regulated by methyltransferases (METTL3, METTL14, and WTAP), demethylases (FTO and ALKBH5), and m6A-binding proteins (such as YTH domain family proteins and IGF2BP family proteins), which are essential for cancer initiation and progression." (PMID 37580808, 2023). "However, the regulatory effects of m6A on cancer microenvironment is controversial, especially for the roles of METTL3 and ALKBH5 in immune cells and non‐immune cells." (PMID 36260366, 2023). "In this study, we report that RNA demethylase ALKBH5 regulates endoplasmic reticulum (ER) homeostasis and adaptive survival mechanism by controlling the unfolded protein response (UPR), autophagy, and mitochondrial function in normal and cancer cells." (PMID 37174684, 2023). "Additionally, RNA modification genes, such as RBMX, HNRNPC, ALKBH5, and WTAP, play a crucial role in cancer biology." (PMID 38055673, 2023). "ALKBH5 is also overexpressed within LSCC and influences the m6A-methylated level of KCNQ1OT1 through modulating specific positions upon KCNQ1OT1, modulating cancer cell proliferation, invasion and metastasis." (PMID 37816718, 2023). "Therefore, an improved methodology is needed to fully explore the exact context of the role of ALKBH5 and FTO in cancer, especially for those cancers where the role of ALKBH5 and FTO is highly controversial." (PMID 37007161, 2023). "Functional assays indicated an anti-cancer role of FTO and ALKBH5 in CRC." (PMID 37580808, 2023). "Two studies investigated the co-expression of ALKBH5 and FTO in cancers." (PMID 36582218, 2023). "GEPIA2 database analysis of the pan-cancer cohorts showed that OS was significantly reduced in BLCA (HR=1.5), LAML (HR=2.0), LGG (HR=1.6), and UVM (HR=4.9) patients with high ALKBH5 mRNA expression levels and significantly increased in CESC (HR=0.62) patients with high ALKBH5 mRNA expression levels." (PMID 35444654, 2022). "Therefore, we investigated the relationship between ALKBH5 expression levels and MSI, TMB or neoantigens to determine if ALKBH5 was a predictor of immunotherapeutic responses in multiple cancer types." (PMID 35444654, 2022). "In addition, the Wnt/β-catenin signaling pathway, the m6a “eraser” ALKBH5, and miR-3436 were reported to regulate YTHDF1 expression in cancers." (PMID 35197112, 2022). "Moreover, proteins responsible for m6A modification, including writers (such as METTL3/14), erasers (such as FTO and ALKBH5), and readers (such as YTHDF1/2/3), have been found to be overexpressed and promote the initiation and development of many cancer types." (PMID 35986274, 2022). "m6A methylation requires multiple protein complexes in the cell to complete, including writers (METTL3, METTL14, and WTAP), erasers (ALKBH5), and readers, among which METTL3 is involved in cancer progression by regulating the expression of a variety of cancer-related genes." (PMID 36347844, 2022). "ALKBH5, as RNA demethylase, was found high-expressed in various types of cancers and considered a negative prognosis biomarker." (PMID 36566230, 2022). "ALKBH5 demethylated and stabilized m6A modification target oncogenes in KRAS mutant cancers, which may influence how vulnerable the cancer is to therapy." (PMID 34016959, 2021).
cancer (continued). "In other cancer types, the role of ALKBH5 in resistance to radiotherapy has never been reported and only one study on cervical cancer has reported the role of the mRNA demethylase FTO on radioresistance." (PMID 33375621, 2020). "RNA methyltransferases (such as METTL14, METTL3 and TAP), the demethylases(such as ALKBH5 and FTO), and the binding proteins (such as YTHDF2 and YTHDF1) are often upregulated in a variety of human cancer types to increase the expression of oncogenes and oncoproteins." (PMID 33136551, 2020). "However, it seems that ALKBH5 and FTO can have an opposite role in other cancer types, suggesting a complex regulation system." (PMID 33375621, 2020). "Indeed, increasing m6A through knocking down adenosine demethylases (FTO and ALKBH5) or overexpressing adenosine methyltransferases (METTL3 and METTL14) suppressed the cancer cell proliferation." (PMID 29228737, 2017). "Although several inhibitors like IOX3 17, MV1035 18, ALK-04 19 have been developed to target ALKBH5, none have received clinical approval for cancer treatment, likely due to issues with target specificity, therapeutic effectiveness, safety, and pharmacokinetics." (PMID 39990235, 2025). "However, studies indicated that ALKBH5 has a dual role in cancer, as its expression is not consistently upregulated or downregulated across all cancer types." (PMID 39054967, 2024). "Both ALKBH5 and FTO can regulate the cancer epigenome through demethylation of mRNA m6A, leading to changes in the ability of cells to survive, proliferate, invade, and metastasize as alterations in drug sensitivity, cancer stem cell status, and cancer immunity." (PMID 37007161, 2023). "Notably, ALKBH5 is not merely a passive marker; it actively modulates oncogenic processes, playing a crucial role in both the proliferation and invasion of cancer cells." (PMID 38148841, 2023). "Consequently, the ALKBH5-cIDR-mediated phase separation contributes to a positive feedback loop between incorporation into PS and NEAT1 demethylation, which fosters PS assembly and cancer cell adaptation to hypoxia." (PMID 37474102, 2023). "It is also plausible that, unlike normal cells, cancer cells may be more addicted to ALKBH5, meaning they are more sensitive to changes in the levels of ALKBH5, and consequently, to the extent of the UPR activation." (PMID 37174684, 2023). "We first demonstrated the function of ALKBH5 in facilitating HNSCC progression and the regulation of IFNα secretion to promote immune escape via m6A modification, which provides new insights into carcinogenesis and a novel potential target for cancer treatment." (PMID 35395767, 2022). "Our results revealed that in GBM cancer cells, expression of CD274 (PD-L1), PDCD1LG2 (PD-L2), LGALS9 (Galectin-9), and PVR (CD155) were positively correlated with the expression of multiple m6A regulators, especially YTHDF2, YTHDF3, LRPPRC, METTL3, RBM15B, FTO, and ALKBH5." (PMID 35558067, 2022). "Noticeably, inhibitors of FTO and ALKBH5 are effective in certain subtypes of AMLs and some solid tumors where FTO or ALKBH5 is overexpressed and promotes tumorigenesis, suggesting that these inhibitors may have promising and broad roles in cancer therapy." (PMID 34381710, 2021). "However, ALKBH5 and FTO have been reported as a tumor suppressor by inhibiting cancer progression." (PMID 32884942, 2020). "The role of ALKBH5 in radioresistance of GBM or other cancer types has never been reported." (PMID 33375621, 2020). "Evidences have found that ALKBH5 and FTO could promote cancer tumorigenesis." (PMID 32884942, 2020). "The mechanisms of ALKBH5 were involved in human cancers and non-cancers." (PMID 32742194, 2020). "However, further researches are still needed to illuminate the exact details of ALKBH5 expression and its mechanisms in human cancers and non-cancers." (PMID 32742194, 2020). "In addition to ALKBH5, FTO could also affect cancer biology by targeting lncRNAs." (PMID 38075202, 2024).